FABP3 (fatty acid binding protein 3)
Diseases named in the same sentence as FABP3 in open-access papers (continued):
Sharing a sentence is not in itself a finding about the gene and the disease.
synucleinopathies (continued). "Here, we showed that FABP3 may initiate the development of α-synucleinopathies following the injection of mouse α-Syn PFF in dopaminergic neurons in the SNpc." (PMID 32210174, 2020). "Taken together, FABP3 largely mediates α-Syn toxicity in the synucleinopathies condition." (PMID 32210174, 2020). "We next examined whether αSyn fibrils were colocalized with FABP3 in synucleinopathies." (PMID 33841128, 2021). "We next examined whether phosphorylated αSyn (p-αSyn) colocalized with FABP3 in synucleinopathies." (PMID 33841128, 2021). "Therefore, αSyn aggregates and FABP3 may interact with each other and play a key role in the pathogeneses of synucleinopathies." (PMID 33841128, 2021). "Thus, FABP3 may partly contribute to cognitive impairments due to septal GABAergic lesions in synucleinopathies." (PMID 33401521, 2021). "However, our results provide important evidence for the development of novel therapeutics for α-synucleinopathies, such as the FABP3 inhibitor MF1, which could block human α-Syn-injected pathologies." (PMID 32210174, 2020). "MF1 attenuates aggregation and spreading of α-synuclein by preventing interactions between FABP3 and α-synuclein, suggesting that MF1 has the potential for early treatment of α-synucleinopathies." (PMID 32752296, 2020). "Overall, FABP3 enhances α-Syn spreading in the brain following α-Syn PFF injection, and the FABP3 ligand MF1 represents an attractive therapeutic candidate for α-synucleinopathy." (PMID 32210174, 2020). "Our observations suggest that FABP3 is a therapeutic target for PD and that the FABP3 ligand MF1 may be an attractive candidate for blocking the progression of α-synucleinopathies." (PMID 32210174, 2020).
Stroke (15 papers, 2009 to 2025). Sudden impairment of blood flow to a part of the brain due to occlusion or rupture of an artery to the brain. "Moreover, given that the deposition of αSyn protein has been discovered in the neurons of stroke patients, and that FABP3 plays a pivotal role in αSyn oligomerization, it would appear very likely that the induction of αSyn neurotoxicity is one of the injury-related mechanisms of FABP3." (PMID 36077044, 2022).
Hypertension (13 papers, 2014 to 2026). The presence of chronic increased pressure in the systemic arterial system. "The results of simple linear regression analysis showed that FABP3 was positively associated with age, duration of schizophrenia, hypertension, and creatinine." (PMID 37255976, 2023). "The array of systemic changes in CVD-related biomarkers included increased blood levels of hypertension marker aldosterone, elevated FABP3, a biomarker of heart pathology, and significantly increased vascular markers IL-16 and ST2." (PMID 32804947, 2020).
atherosclerosis (12 papers, 2011 to 2025). A disease characterized by the build-up of fatty material and calcium deposition in the arterial wall resulting in partial or complete occlusion of the arterial lumen. "Previous studies suggest that FABP3 is associated with atherosclerosis." (PMID 38218337, 2024). "Reduced activity of SERPINE1, therefore, suggests that loss of FABP3’s function prompts endothelial cells away from a state of senescence and improves clot breakage, providing benefits against cardiovascular risk in aging and dysregulated clot formation in atherosclerosis." (PMID 36681124, 2023). "Circulating FABP3 will also be measured following crossing FABP3endo mice with ApoEnull mice (FABP3endo:ApoEnull) and feeding them high-fat diet to induce atherosclerosis." (PMID 36681124, 2023). "In rat atherosclerosis PCR array, Abca1, Bax, Bcl2, Bcl2a1, Cd44, Fabp3, Hbegf, Lypla1, Ptgs1, Selplg, Tgfb2, Tnc, and Vegfa had reverse trend between WT and MU groups, while the trends of Bcl2l1, Bid, Birc3, Cxcl1, Fas, Fn1, Itga2, Itga5, Lif, Nfkb1, Nr1h3, Ppard, and Sod1 were consistent." (PMID 34545275, 2021). "This suggests a possible rise of blood FABP3 independent of myocardial injury and, while the source of this FABP3 release is not known, we suspect ECs for their close connection between endothelial dysfunction in atherosclerosis." (PMID 33105856, 2020).
Insulin resistance (12 papers, 2004 to 2025). Increased resistance towards insulin, that is, diminished effectiveness of insulin in reducing blood glucose levels. "In previous works, FABP3 has been related to the control of cardiac insulin resistance and fatty acid uptake, but also as an independent predictor for the occurrence of all-cause and CV mortality in T2D patients with HF." (PMID 38978010, 2024).
Cognitive impairment (10 papers, 2013 to 2023). Abnormal cognition is characterized by deficits in thinking, reasoning, or remembering. "This study aimed to evaluate the relationship between the CSF levels of FABP3 and ApoE4 proteins and cognitive decline as well as the diagnostic performance of these candidate biomarkers in AD and mild cognitive impairment (MCI)." (PMID 34300173, 2021). "This evidence supports the idea that FABP3 is linked to the neurodegeneration process and cognitive impairment occurring at later stages and is more evident in patients with PDD." (PMID 28750675, 2017). "Notably, Fabp3 deletion antagonized the accumulation of phosphorylated αSyn, decrease in GABAergic neurons, and cognitive impairment caused by αSyn fibrils." (PMID 33401521, 2021). "Finally, we investigated the effects of Fabp3 deletion on cognitive impairments caused by intrastriatal injection of αSyn fibrils." (PMID 33401521, 2021). "αSyn pathology was well correlated with distinct localization of FABP3 in the MS/DB, and Fabp3 deletion potently inhibited the pathology and cognitive impairments." (PMID 33401521, 2021). "In conclusion, the present study documented that FABP3 partly contributes to αSyn propagation in GABAergic neurons in the MS/DB and cognitive impairments seen in mice injected intrastriatally with αSyn fibrils." (PMID 33401521, 2021). "Notably, FABP3 was highly expressed in GABAergic neurons in the MS/DB, and its deletion antagonized αSyn fibril-induced cytotoxicity in GABAergic neurons and cognitive impairment." (PMID 33401521, 2021). "Fabp3 null mice also exhibited cognitive impairment, increased daytime locomotor activity, which may reflect sleep disturbance, and anxiety behaviors, suggesting that Fabp3 null mice may display PTSD-like behaviors." (PMID 31344835, 2019). "The αSyn cytotoxicity and the resultant Parkinsonism was antagonized in Fabp3−/− mice, by treatment with a competitive inhibitor of LC-PUFAs binding to FABP3; however, it remains unclear whether FABP3 is also related to αSyn-induced cognitive impairment and septal αSyn pathology." (PMID 33401521, 2021). "In APOE ε4 non-carriers, most of these protein levels were similar to controls, except for inflammation markers SPP1, FABP3 (also in the replication cohort), and GFAP that were higher in more severe stages of cognitive impairment." (PMID 32460813, 2020). "Two weeks after injection of mouse α-Syn PFF, wild-type (WT) mice exhibited motor and cognitive deficits, whereas FABP3 knock-out (Fabp3−/−) mice did not." (PMID 32210174, 2020). "Finally, we confirmed that the novel FABP3 inhibitor MF1 significantly antagonized motor and cognitive impairments by preventing α-Syn spreading following α-Syn PFF injection." (PMID 32210174, 2020). "Bilateral injection of α-Syn PFF into the SNpc induced motor and cognitive impairments in WT but not Fabp3−/− mice." (PMID 32210174, 2020). "Therefore, the present study aimed to measure the concentrations of ApoE4 and FABP3 in cerebrospinal fluid of patients with AD, MCI and non-demented subjects (CTRL) and compare them to classical biomarkers and a clinical score of cognitive impairment." (PMID 34300173, 2021).
Parkinson disease (10 papers, 2017 to 2025). A progressive degenerative disorder of the central nervous system characterized by loss of dopamine producing neurons in the substantia nigra and the presence of Lewy bodies in the substantia nigra and locus coeruleus. "FABP3 was found to be essential for the intracellular accumulation and oligomerization of α-synuclein, a pathogenic protein in Parkinson’s disease, as well as for its propagation in the brain." (PMID 38069360, 2023). "Previously, certain reports have suggested methods to predict Parkinson’s disease using FABP3 as a biomarker in the cerebrospinal fluid or serum." (PMID 38069360, 2023). "Since FABP3 is highly expressed in these neurons, we have proposed the protein as a potential enhancer of αSyn pathology and Parkinsonism." (PMID 33401521, 2021). "These clinical findings suggest that FABP3 may be involved in the pathogenesis of Lewy body diseases, including Parkinson’s disease." (PMID 38069360, 2023). "FABP3 is abundantly expressed in dopaminergic neurons within the central nervous system and is immunopositive in intracellular inclusions in model cells and in Lewy bodies in patients with Parkinson’s disease." (PMID 38069360, 2023). "In addition, FABP3 expression in the substantia nigra is known to be increased in autopsy brains of Parkinson’s disease patients." (PMID 38069360, 2023). "The expression sites of FABP3 and D2L receptors in the brain, such as the midbrain, olfactory bulb, and cerebral cortex, correspond to the regions where Lewy bodies are observed in Parkinson’s disease and Lewy body dementia." (PMID 38069360, 2023). "We propose that administration of αSynP130-140 might be used to prevent the accumulation of toxic FABP3-αSyn oligomers in cells, thereby preventing the progression of Parkinson’s disease." (PMID 33862084, 2021). "Thus, the involvement of FABP3 in the etiology of Parkinson’s disease and unveiling its mechanism are anticipated to be elucidated." (PMID 33429895, 2021). "Furthermore, FABP3 is an expected biomarker for Parkinson’s disease because it increases in the patients’ plasma." (PMID 33429895, 2021). "Among these ligands, we confirmed that MF1 and MF8 could target FABP3 and improve motor deficits and cognitive impairments in a mouse model of MPTP-induced Parkinson’s disease." (PMID 34068550, 2021). "Notably, the absence of FABP3 prevents the loss of mitochondrial membrane potential, abolishing the generation of stress response factors such as 4-hydroxynonenal (4-HNE), which plays an essential role in the degeneration of dopaminergic neurons in Parkinson’s disease." (PMID 38069360, 2023).
peripheral arterial disease (10 papers, 2021 to 2026). A disorder of the arteries supplying the upper and lower extremity and the visceral organs. "Elevated levels of FABP3 are indicative of a poor prognosis in several cancers and are increased in peripheral artery disease, referring back to the accepted association of angiogenesis in tumor progression." (PMID 40072060, 2025). "In the literature, FABP3 has been shown to be a promising clinical biomarker for coronary and peripheral artery disease." (PMID 36140383, 2022). "In this review, we highlight key discoveries and recent studies on the role of FABP3 in cardiovascular disorders, with a particular focus on its clinical relevance as a biomarker for peripheral artery disease." (PMID 36140383, 2022). "Interestingly, its high sensitivity for striated muscle damage is illustrated by its evolving role as an accepted novel biomarker for peripheral arterial disease, where repetitive tissue ischemia and reperfusion lead to an acquired myopathy with FABP3 elevation." (PMID 39795963, 2024). "Accordingly, recently we identified increased circulating levels of FABP3 in peripheral arterial disease (PAD) patients with severe inflammation and particularly undergoing critical limb ischemia, who were negative for any signs of cardiac damage." (PMID 36681124, 2023).
Sepsis (10 papers, 2013 to 2025). Sepsis is defined as life-threatening organ dysfunction caused by a dysregulated host response to infection. "To evaluate the relevance of our LPS-associated in vitro data in an animal model of sepsis, we treated wildtype mice with LPS and measured circulatory FABP3." (PMID 36681124, 2023). "The source of LPS-induced FABP3 in mouse plasma is still unknown, but if true in humans, then FABP3 might also provide a biomarker for the severity of sepsis in humans, which warrants future investigations." (PMID 36681124, 2023). "In addition, previous studies have shown that FABP3 may be useful to detect other conditions such as pulmonary thromboembolism, sepsis and congestive cardiac failure." (PMID 37255976, 2023).
stable angina (10 papers, 2014 to 2024). "In this study, we also found that a high FABP3 level was significantly associated with the occurrence of all-cause mortality in patients with stable angina and that a higher FABP3 level was positively associated with the plasma level of adiponectin." (PMID 33850478, 2021). "Therefore, the aim of this study was to investigate whether FABP3 levels were associated with a prolonged QTc interval and reduced EF in a cohort of patients with stable angina." (PMID 33850478, 2021). "Furthermore, our previous studies found that plasma FABP3 could be used as a surrogate for reduced ejection fraction and abnormal corrected QT (QTc) interval, and that in patients with stable angina, plasma FABP4 level may also be associated with an abnormal QTc interval." (PMID 37255976, 2023). "In the current study, we found that plasma FABP3 levels were positively related to QTc interval in patients with stable angina and significantly increased in the patients with an abnormal QTc interval compared to those with borderline and normal QTc intervals." (PMID 33850478, 2021). "This study aimed to investigate the relationship between plasma FABP3 level and prolonged corrected QT (QTc) interval and reduced EF in patients with stable angina." (PMID 33850478, 2021). "In this study, a higher FABP3 level was independently associated with plasma levels of hs-CRP, visfatin, and WBC count, which suggests that FABP3 may act through inflammatory responses to play an important role in the pathophysiology of reduced EF in patients with stable angina." (PMID 33850478, 2021).
acute kidney injury (8 papers, 2014 to 2024). Sudden and sustained deterioration of the kidney function characterized by decreased glomerular filtration rate, increased serum creatinine or oliguria. "The amount of FABP3 in urine of patients with acute kidney injury was suggested as diagnostic/prognosis marker for renal replacement therapy." (PMID 36333282, 2022).
chronic heart failure (8 papers, 2011 to 2023). "In this regard, AKI and ischemic tubular risk have been directly linked to increments in urinary FABP-1 and FABP-3 levels, and in patients with chronic heart failure, elevated FABP-3 levels have been associated with elevated cardiovascular occurrence." (PMID 37529809, 2023).
gastric cancer (8 papers, 2016 to 2025). A primary or metastatic malignant neoplasm involving the stomach. "On the other hand, elevated FABP3 expression is associated with tumor progression, aggressiveness and poor prognosis in gastric carcinoma." (PMID 27323829, 2016). "FABP3 has emerged as a consistent high-risk prognostic marker in gastric cancer (GC), identified across multiple studies through transcriptomic analyses, survival modelling, and functional validation." (PMID 41149452, 2025). "In gastric cancer patients with cancer-associated cachexia (CAC), plasma levels of FABP3 are significantly elevated, suggesting its potential role in cancer-related muscle wasting." (PMID 40717587, 2025). "Increased FABP3 expression has been reported to be involved in the progression and aggressiveness of gastric cancer." (PMID 36478991, 2022). "Tumor immune microenvironment: FABP3 is involved in a copper death-related immune signature and plays a role in prognosis prediction for gastric cancer patients, potentially influencing disease progression through regulation of the tumor immune microenvironment." (PMID 40717587, 2025). "In NSCLC the prognostic role of FABP3 is not known, while in gastric cancer, high expression of heart-type FABP protein is associated with increased tumoraggressiveness, metastasis and poor prognosis." (PMID 27081700, 2016).
glioblastoma (8 papers, 2018 to 2025). The most malignant astrocytic tumor (WHO grade IV). "CooP binds to the mammary-derived growth inhibitor/fatty acid binding protein 3 (FABP3) in the glioblastoma cells and its associated vasculature." (PMID 32650473, 2020). "In summary, we have performed alanine scanning to create glioblastoma homing peptide A-CooP variants and have analyzed their binding to the target protein FABP3 by using MST." (PMID 32650473, 2020). "Here, we describe measurements of binding affinity between the A-CooP peptide and recombinant FABP3, reveal essential amino acids required for binding, and show improved affinity of the A-CooP-K variant towards FABP3, leading to improved glioblastoma targeting." (PMID 32650473, 2020). "The glioblastoma homing peptide, CooP, was identified by using the in vivo phage display, and FABP3/MDGI was identified as its binding partner." (PMID 32650473, 2020). "Our approach suggested A-CooP-K as a novel theranostic tool for glioblastoma detection and treatment due to the 30-fold enhanced binding affinity towards target (FABP3) compared to the original A-CooP peptide." (PMID 32650473, 2020). "For this purpose, FABP3 was overexpressed as a green fluorescent protein (GFP)-fusion (FABP3-GFP) in the U87MG glioblastoma cells that show low endogenous FABP3 expression." (PMID 32650473, 2020). "We aimed to understand the role of each amino acid in the A-CooP sequence on the binding to FABP3 in the context of glioblastoma targeting." (PMID 32650473, 2020). "Consistent with this, MDGI/FABP3 expression was highest in the mesenchymal subtype of glioblastomas (GlioVis) as well as in the leading edge and infiltrating tumour cells based on tumour structure‐specific mRNA expression dataset of glioblastomas (Ivy_GAP)." (PMID 31068339, 2019). "It identifies the heart‐type fatty acid binding protein (MDGI/FABP3) as a central regulator of the lysosomal membrane integrity in glioblastoma cells." (PMID 31068339, 2019). "The CooP peptide is a glioblastoma homing peptide identified, such as Lyp-1 by the in vivo selection of a phage display peptide library, whose interacting partner has been identified primarily to be the mammary-derived growth inhibitor (MDGI/FABP3)." (PMID 34638864, 2021). "Furthermore, we used both in vitro and in vivo glioblastoma models to validate the FABP3-dependent binding of fluorescently labeled CooP and its analogues." (PMID 32650473, 2020). "We analysed MDGI/FABP3 expression in The Cancer Genome Atlas (TCGA) RNA seq datasets for glioblastoma (TCGA GBM) and for glioblastoma and low‐grade glioma (TCGA GBMLGG)." (PMID 31068339, 2019). "The CooP peptide has been selected by the in vivo screening of a phage display library and classified as a glioblastoma homing peptide, with the mammary-derived growth inhibitor (MDGI/FABP3) identified as its interacting partner." (PMID 37240259, 2023). "On the basis of in silico simulations, it was hypothesized that DOX-TBSV-CooP NP internalization by MB cells could be mediated by MDGI/FABP3, the receptor expressed on glioblastoma cells recognized by CooP." (PMID 37240259, 2023). "Indeed, fluorescently labeled A-CooP-K also showed significant uptake in the U87MG glioblastoma cells overexpressing the FABP3-GFP fusion protein compared to U87MG expressing GFP, suggesting that the binding was FABP3 dependent." (PMID 32650473, 2020).
ischemic stroke (8 papers, 2013 to 2026). A stroke disorder caused by obstruction of blood flow to the brain, due to thrombotic (local blood clot formation) or embolic (due to a blood clot or other material traveling from another site) event. "Targeting FABP3 may provide a potential therapeutic strategy for neuroprotection in ischemic stroke." (PMID 42274596, 2026).